FGF23 (fibroblast growth factor 23)
Diseases named in the same sentence as FGF23 in open-access papers (continued):
Sharing a sentence is not in itself a finding about the gene and the disease.
anemia (continued). "Therefore, the anemia of CKD is a potent stimulator of FGF23, as improvement of iron utilization via exogenous EPO administration, or endogenous EPO stimulation in mice treated with a HIF‐PHDi, markedly attenuated the increase in circulating iFGF23 concentrations." (PMID 32476270, 2020). "We further investigated whether FGF23 levels increase the future development of anemia." (PMID 29740119, 2018). "Furthermore, in patients without anemia at baseline, elevated FGF23 levels were associated with an increased risk of new development of anemia." (PMID 29740119, 2018). "In most studies, the causality between FGF23 and anemia could not be explained because this relationship was analyzed through a cross-sectional approach." (PMID 29740119, 2018). "Furthermore, all dying mice had severe anaemia, low hepcidin levels and high FGF23 levels." (PMID 29338760, 2018). "The data do not allow a conclusion on whether the high FGF23 levels in these mice were primarily caused by anaemia or inflammation." (PMID 29338760, 2018). "Therefore, in addition to reducing PTH, reduction of fibroblast growth factor 23 may be one pathway through which cinacalcet improves anemia." (PMID 27764168, 2016). "FGF23 has been indicated to contribute to hepcidin expression during inflammation, resulting in FID and anemia." (PMID 39336155, 2024). "Another molecule that plays an important role in CKD-MBD is fibroblast growth factor (FGF)-23, whose main role is to maintain serum phosphate levels in the normal range, acting via its co-receptor Klotho; however, its activity may also be related to anemia and inflammation." (PMID 39684548, 2024). "Notably, neutralization of the increased serum levels of fibroblast growth factor 23 (FGF23), a regulator of phosphate homeostasis and bone mineralization and an inhibitor of erythropoiesis, restored bone microarchitecture and improved osteoid mineralization and anemia." (PMID 36761941, 2023). "Fibroblast growth factor-23 (FGF23), a hormone that regulates bone metabolism, is assumed to be the key factor linking CKD-MBD and anemia." (PMID 37605118, 2023). "On the other hand, anemia is common in patients with CKD, and targeted therapy against it, for example, erythropoietin (EPO)–stimulating agent treatment, can induce increased FGF23 serum levels." (PMID 35966090, 2022). "Anemia is a serious complication in CKD patients, in which elevations of FGF23 levels are an early feature." (PMID 36432528, 2022). "The resulting endocrine profile that characterizes patients with CKD –high FGF-23 and PTH, with low calcitriol and α-Klotho—contributes to cardiovascular morbidity, systemic inflammation, dysregulation of bone metabolism, and anemia." (PMID 35602513, 2022). "FGF23 knockout mice became polycythemic through decreased apoptosis of erythroid progenitor cells and increased erythropoietin (EPO), whereas administration of FGF23 decreased endogenous EPO and exacerbated anaemia." (PMID 33832448, 2021). "We were intrigued by these findings as increased plasma FGF23 and EPO levels are often observed in anemia." (PMID 34362888, 2021). "We further show that genetic deletion of LCN2 in mice that develop CKD prevented increases in bone and circulating levels of FGF23 and development of LVH, and improved lifespan, despite CKD and anemia of unchanged severity." (PMID 34334787, 2021). "Thus, improvement of iron utilization in a CKD model using EPO and a HIF‐PHDi significantly reduced iFGF23, demonstrating that anemia is a primary driver of FGF23, and that management of iron utilization in patients with CKD may translate to modifiable outcomes in mineral metabolism." (PMID 32476270, 2020). "Recent research has revealed bidirectional relationships between bone-secreted fibroblast growth factor 23 (FGF23), inflammation, iron status, and anemia." (PMID 33392212, 2020).
anemia (continued). "In this review, we will examine the current experimental and clinical evidence regarding the role of FGF23 in renal physiology as well as in the pathophysiology of CKD with an emphasis on chronic inflammation and anemia." (PMID 31461904, 2019). "In conclusion, this study showed that serum FGF23 levels were inversely correlated with hemoglobin levels in patients with CKD and that patients with high FGF23 levels were more likely to have anemia." (PMID 29740119, 2018). "Considering the positive correlation between the serum FGF-23 levels and PTH, FGF-23 is believed to contribute to the development of anemia in dialysis patients." (PMID 25295189, 2014). "Further research is necessary in order to demonstrate whether i-FGF23 contributes to FID and anemia through the hepcidin molecular pathway in acute infections in vivo." (PMID 39336155, 2024). "In addition, the uremic milieu also includes other hypertrophic stimuli such as fibroblast growth factor 23, uremic toxins, CKD mineral bone disorder and anaemia." (PMID 38203544, 2023). "Although we showed that CRISPR deletion of Phd2 had marked effects on Fgf23 expressional control in response to mimicked hypoxia and anemia, we did not directly investigate the consequences of Phd1 or Phd3 deletion in vitro." (PMID 36650133, 2023). "The Wnt signaling pathway and its downstream angiocrine target molecules such as FGF23 and DKK2 may also bear therapeutic potential in various types of anemia or in hematopoietic neoplasms." (PMID 34845225, 2021). "Increased plasma FGF23 and EPO levels are often observed in anemia." (PMID 34362888, 2021). "Ctnnb1OE-SEC BM-SEC reveal aberrant sinusoidal differentiation with altered EC gene expression and perisinusoidal ECM deposition and angiocrine dysregulation with de novo endothelial expression of FGF23 and DKK2, elevated in anemia and involved in vascular stabilization, respectively." (PMID 34845225, 2021). "Deletion of Lcn2 in CKD mice did not improve kidney function or anemia but prevented the development of LVH and improved survival in association with marked reductions in serum FGF23." (PMID 34334787, 2021). "It remains unclear if and how bile acid toxicity induces anemia of chronic disease leading to the increase in EPO and FGF23." (PMID 34362888, 2021). "Fibroblast growth factor 23 (FGF23), a key-player in mineral metabolism, is reportedly associated with anemia and hemoglobin levels in non-dialysis CKD patients." (PMID 32823844, 2020). "In this study, however, the effect of FGF23 on the development of anemia was not altered after adjustment for 1,25-dihydroxyvitamin D3 levels." (PMID 29740119, 2018). "Plasma FGF23 and 1,25(OH)2D concentrations were higher in children with anaemia compared to those without (P ≤ 0.0001 and P = 0.03 respectively)." (PMID 22465847, 2012). "Our initial hypothesis was that i-FGF23 promotes hepcidin expression during acute infection, leading to hypoferremia and subsequently anemia in pediatric patients without comorbidities." (PMID 39336155, 2024). "Second, we have not examined factors that link CKD-MBD and anemia, such as FGF23 and hepcidin." (PMID 37605118, 2023). "Considering that FGF23 and anemia are nontraditional risk factors for adverse outcomes in patients with CKD, and both are reciprocally changed according to kidney function, it would be intriguing to explore the relationship between FGF23 and anemia in CKD." (PMID 29740119, 2018). "MM-related anemia is due to impaired iron utilization, rather than low iron per se, with most MM patients having normal or high iron status, making it unlikely to explain high FGF23." (PMID 25944690, 2015). "After supplementation, the prevalence of elevated FGF23 was 16% (P=0.1), the prevalence of anaemia had decreased to 62% (P=0.0005), there were no subjects with low Ferr (P≤0.0001) and the frequency of subjects with CRP ≥ 5 mg/dL did not significantly change (P=1.0)." (PMID 23098062, 2012).
anemia (continued). "However, it is not yet clear if the effects of FGF23 and P are independent and whether the levels of one can modify the effects of the other on anemia." (PMID 36432528, 2022). "However, the contribution of anemia to overall circulating FGF23 levels in CKD is not understood." (PMID 32476270, 2020). "This study suggested that under conditions of anemia, as opposed to mice with normal iron homeostasis, rescuing iron utilization during CKD may be a more potent suppressor of FGF23 than EPO and HIF-PHIs are stimulators." (PMID 32982979, 2020). "However, this inverse interrelationship between i-FGF23 and hepcidin is not sufficient to demonstrate clearly whether i-FGF23 contributes to FID and anemia through the hepcidin molecular pathway in acute pediatric infections." (PMID 39336155, 2024). "FGF23 is regulated at the transcriptional and posttranscriptional levels by several bone mineral factors, including phosphate (via glycerol-3-phosphate and lysophosphatidic acid), calcium, vitamin D, and parathyroid hormone (PTH), and nonmineral factors like anemia, inflammation, and metabolism." (PMID 37681408, 2023).
renal failure (98 papers, 2008 to 2026). "The use of phosphate binders was associated with a lower risk of incident dementia, and a higher serum fibroblast growth factor-23 (FGF23) level was cross-sectionally associated with lower cognitive function in patients with kidney failure." (PMID 39519609, 2024). "Patients with CKD and kidney failure display higher FGF23 levels due to the strong association between FGF23 and kidney function." (PMID 34960084, 2021). "Confirming previous in vivo and clinical studies of patients with renal insufficiency, we observed a positive association between FGF23 and PTH." (PMID 33640873, 2021). "Since the increase in blood levels of FGF-23 is known to associate with kidney failure, we further investigated the mechanisms leading to sepsis-induced decrease in blood levels of IGF-1." (PMID 31791247, 2019). "Since the increase in blood FGF-23 levels is known to associate with kidney failure, we further investigated the mechanisms leading to the sepsis-induced decrease in blood IGF-1 levels." (PMID 31791247, 2019). "In the observational Chronic Renal Insufficiency Cohort (CRIC) study in 3,879 participants with CKD stages 2-3, FGF23 was an independent risk factor for kidney failure and death." (PMID 26491212, 2015). "Together, our data indicates two different models of experimental kidney failure comparably associate with disturbed FGF23-αklotho-vitamin-D signalling and a deregulated electrolyte homeostasis." (PMID 26566277, 2015). "In our current prospective cohort of chronic dialysis patients, we found higher plasma FGF-23 concentrations to be directly associated with a decrease in LV EF during the study follow-up." (PMID 23849306, 2013). "FGF23 is associated with progression of kidney failure and initiation of dialysis." (PMID 32130720, 2020). "Consequently, the decreased blood levels of IGF-1, increased blood levels of FGF-23, and kidney failure cause suppressed activity of kidney 1α-hydroxylase, leading to reduced production of 1,25(OH)2D in kidney and decreased 1,25(OH)2D levels in blood." (PMID 31791247, 2019). "Thus, PTH and FGF23 have been implicated as key players in mediating the observed changes in skeletal metabolism during kidney failure." (PMID 29394885, 2018). "Then, they discussed the dysregulated actions of fibroblast growth factor 23 (FGF23), which contributes to various inherited diseases and mortality in kidney failure patients." (PMID 37920253, 2023). "In patients with kidney failure, FGF23 loses its ability to stimulate urinary phosphate excretion and inhibit 1,25D production." (PMID 36977891, 2023). "Elevated serum levels of FGF-23 and sclerostin are seen along with higher bone expressions in renal insufficiency." (PMID 36970967, 2023). "In the early stage of renal insufficiency, the body compensates by increasing FGF23 to inhibit the synthesis of 1,25(OH)2VitD3 and promote urinary phosphorus excretion in order to maintain normal blood phosphorus levels." (PMID 36649363, 2023). "Renal insufficiency, classified by low eGFR, led to an elevation of fibroblast growth factor 23 (FGF23) as early as stage 3 chronic kidney disease." (PMID 36759556, 2023). "The obtained results confirm prior observations of increased blood levels of FGF-23 and sclerostin in patients with renal insufficiency." (PMID 36970967, 2023). "In a retrospective case–control study in 24 pediatric CKD patients with kidney failure the relevance of FGF23 on cardiac fibrosis was evaluated." (PMID 34422725, 2021). "In early CKD, circulating FGF23 levels rise exponentially and are up-to 1,000-fold enhanced in kidney failure." (PMID 34422725, 2021). "In a previous report, ADPKD patients demonstrated inappropriately high FGF23 levels compared to the severity of their renal insufficiency." (PMID 32178226, 2020). "Such disorders include decreased serum IGF-1 levels, kidney failure as indicated by the increased blood creatinine levels, and increased blood FGF-23 levels." (PMID 31791247, 2019).
renal failure (continued). "Further studies showed that this failure of PTH to maintain blood 1,25(OH)2D levels was associated with decreased blood levels of IGF-1, increased blood levels of FGF-23, and kidney failure." (PMID 31791247, 2019). "Recently, significant attention has been focused on FGF23 and its relationship to phosphate homeostasis in patients with renal insufficiency." (PMID 28497083, 2017). "In non-dialysis CKD, observational studies show that serum levels of Sclerostin increase along with the stages of renal failure and correlate positively with serum FGF23 and phosphate." (PMID 28558021, 2017). "FGF23 is associated with cardiovascular (CV) morbidity and mortality in patients with CKD, and is an independent predictor for progression of kidney failure." (PMID 25700931, 2015). "Despite elevated blood FGF23, both kidney failure models augmented renal Cyp27b1 expression, probably due to the observed increase in PTH." (PMID 26566277, 2015). "In our next study, we plan to use a rat model of hearing impairment in kidney failure to test this hypothesis by targeting the expression of FGF23/D-serine in kidney tissue and cochlea, downstream signaling pathways, and its regulation of NMDAR." (PMID 36649363, 2023). "Lately, it is considered that fibroblast growth factor 23 (FGF-23), which increases in kidney failure probably due to increased plasma phosphorus levels, may be responsible for decreasing vitamin D synthesis." (PMID 38075043, 2023). "In a similar study reporting on the relationship between renal insufficiency and increased FGF23 concentration, nephritic rats were injected with recombinant FGF23, a prolonged disappearance curve was observed and the half-life of FGF23 increased from 4 minutes to 12 minutes." (PMID 36353239, 2022). "In this regard, it is intriguing to speculate that the toxic effects of FGF23 are operating in patients with kidney failure but become attenuated during long-term uremia." (PMID 33163716, 2020). "Taken together, our study demonstrated that murine models of partial nephrectomy and ADE-enriched dietary treatment, both, induce kidney failure that closely resembles CKD development, which is associated with disturbed FGF23-αklotho-vitamin-D signalling and a deregulated Ca2+ and Pi homeostasis." (PMID 26566277, 2015). "In order to determine whether induced kidney failure results in altered FGF23-αklotho signalling, we first measured blood FGF23 levels." (PMID 26566277, 2015). "Elevated FGF-23, iPTH, and Hcy levels, which are found beginning in early phases of CKD us, may guide to begin earlier treatment strategies to minimize the progression of kidney failure and its effects as risk factors for CVD and MBD." (PMID 40612843, 2025). "In addition, kidney failure increases FGF-23 levels in blood." (PMID 31791247, 2019). "Based on our findings that the parathyroid glands of PTH-KL−/− mice retained calcium sensitivity and that sHPT developed similarly as in wild-type mice upon induction of renal insufficiency, we reasoned that the parathyroid response to FGF23 might also be preserved in PTH-KL−/− mice." (PMID 24348262, 2013). "When patients reach kidney failure, circulating levels of PTH and FGF23 increase 5- to 10-fold and 10- to 50-fold above normal, respectively." (PMID 36977891, 2023). "Lanthanum hydroxide, a new phosphate binder, delayed the progression of kidney failure, suppressed the development of vascular calcification; decreased serum PTH and FGF23 levels, and significantly suppressed serum phosphorus." (PMID 33928079, 2021). "Calcimimetics turned out to be more effective in lowering FGF23 and with that lowering mortality and CVD events significantly in patients with kidney failure." (PMID 34422725, 2021). "Further study is needed to determine if these results apply to populations with higher FGF-23 levels, such as those with advanced CKD or with kidney failure requiring maintenance hemodialysis." (PMID 33306729, 2020).
renal failure (continued). "Both CKD patients and experimental animal models of kidney failure show increased serum PTH and FGF23 levels." (PMID 30393837, 2019). "In concert with the phosphaturic effects of FGF23 and PTH, both kidney failure models displayed a reduced renal expression of NaPi2a and PIT2, the principal renal type II and III sodium-dependent Pi transporters, respectively." (PMID 26566277, 2015). "In this context we measured FGF23 levels in patients with end-stage liver disease on a liver transplantation waiting list and found that FGF23 concentration was increased even in the absence of renal insufficiency and was associated with the risk of death on the waiting list." (PMID 23825530, 2013). "FGF-23 is an independent predictor for LVH adjusting for eGFR and appears to be the molecular link between the bone’s physiological response to trauma and AKI or an exacerbation of renal insufficiency in frail individuals." (PMID 38919625, 2024). "While FGF23 is unlikely to exert its hormonal, Klotho-dependent effects on classical target organs in kidney failure, there is a possibility that FGF23 exerts nonclassical effects in a Klotho-independent manner." (PMID 36977891, 2023). "Interestingly, there was also a slight increase in 1,25D levels after initiation of dialysis, suggesting that even in patients with kidney failure, CYP27B1 activity is in part functionally inhibited by FGF23." (PMID 36977891, 2023). "In subject without renal insufficiency, serum FGF-23 was not related with CAC and did not affect serum P—CAC association." (PMID 26992166, 2016). "However, little is known about the relationship between FGF23 and CVDs in a diabetic population, particularly without kidney failure." (PMID 37371618, 2023). "This implies that during the inflammatory changes driven by folic acid overload, autocrine or paracrine FGF23 signaling via a canonical FGFR‐Klotho pathway may play only a minor role, in contrast to more chronic models of kidney failure driven by other pathophysiology." (PMID 36967231, 2023). "However, the expression of cardiac FGF23 did not correlate with the amount of cardiac fibrosis in pediatric patients with kidney failure." (PMID 34422725, 2021). "However, this possibility does not fit the observation that elevated FGF23 was associated with mortality in recipients of kidney transplants, most of whom were survivors over a long period of CKD and kidney failure." (PMID 33163716, 2020). "In this setting, experimental data suggest that FGF23 exerts adverse nontarget effects, but it remains to be confirmed whether FGF23 directly contributes to multiple organ injury in patients with kidney failure and whether targeting FGF23 can improve patient outcomes." (PMID 36977891, 2023).